GATA3 (GATA binding protein 3)
Diseases named in the same sentence as GATA3 in open-access papers (continued):
Sharing a sentence is not in itself a finding about the gene and the disease.
breast carcinoma (continued). "We found HR mutations in approximately 15% of the patient cohort (n = 85), compared with 23% for BRCA2, 13% for GATA3, 7% for BRCA1, and 3% for PTEN in the same breast cancer patient cohort." (PMID 36230572, 2022). "In this study, we identified CA12 as one of the ERα target genes whose RNA expression is most correlated with that of ESR1, GATA3 and FOXA1 in breast cancer datasets." (PMID 36358871, 2022). "GATA3, a factor acting as a MUC1 transcriptional regulator in breast cancer cells, was downregulated by ionizing radiation and the addition of melatonin did not modify its transcription." (PMID 35625825, 2022). "In breast cancer, it has been shown that the cooperative action between GATA3 and its cofactors Estrogen Receptor alpha (ER-α) and FOXA1 is important for the luminal breast cancer characterization." (PMID 35154280, 2022). "Likely, LOC645166 has been revealed to recruit NF-κB to increase the transcription level of GATA binding protein 3 (GATA3), thereby inducing the STAT3 signaling pathway, which eventually facilitated ADR resistance in breast cancer cells." (PMID 36613528, 2022). "In liver cancer, KIAA1429 regulated the expression of GATA3 in an m6A-dependent manner, while KIAA1429 played its oncogenic role in breast cancer by regulating CDK1 in an m6A-independent manner." (PMID 35217651, 2022). "GATA3 inhibits prostate cancer progression by upregulating miR-503 expression to repress the oncogenic activity of ZNF217, and abrogates breast cancer metastasis through regulating Semaphorin 3B expression." (PMID 35804829, 2022). "We then looked for FOXA1 and GATA3 binding sites in HCC1954 breast cancer cells by performing chromatin immunoprecipitation sequencing (ChIP-seq) using FOXA1 and GATA3 antibodies in two biological replicates each." (PMID 35331302, 2022). "MGP was verified as a reliable marker with extremely high sensitivity in all subtypes of breast carcinoma (87.3–91.2%), which is comparable to TRPS1 and much higher than GATA3 in HER2+ and TNBC subtypes." (PMID 36284362, 2022). "Prior to IFNγ stimulation, the TFs demonstrating the highest connectivity were dominated by TFs previously identified for regulating facets of breast cancer biology (in black), including SOX9, GATA3, and ETV6." (PMID 35902886, 2022). "MYC also represses lineage-specific transcription factors in mammary tissues, such as GATA3 and ESR1 to drive cancer stem cell-like states in breast cancer." (PMID 36207293, 2022). "INAVA expression is associated with regulating two transcription factors, ELF5 and GATA3, which are important in breast stem cells, and targeting INAVA has therapeutic value in breast cancer." (PMID 35719392, 2022). "Pan-cancer analysis of data from TCGA revealed that GATA3 was overexpressed in tumor tissues than in normal tissues within several carcinomas, including BLCA, breast cancer, and others." (PMID 35647011, 2022). "Previous studies have demonstrated that ELK3 regulates breast cancer metastasis through Zeb-1, MT1-MMP, and GATA3 gene-mediated signaling pathways." (PMID 35409069, 2022). "Currently, GATA-binding protein 3 (GATA3), gross cystic disease fluid protein 15 (GCDFP-15), and mammaglobin are commonly used breast cancer-specific IHC markers in clinical practice." (PMID 36284362, 2022). "GATA3 is a member of the transcription factor GATA family and can be used as a molecular marker of breast cancer." (PMID 35280773, 2022). "A recent study presented GATA3 and MDM2 were synthetically lethal in ER+ breast cancer, where MDM2 was a novel therapeutic target in GATA3‐deficient subsets." (PMID 34146382, 2022). "When using MGP, GATA3, and TRPS1 as a novel IHC panel, 93.0% of breast carcinomas were positive for at least two markers, and only 9 cases were negative for all three markers." (PMID 36284362, 2022). "Prompted by the findings derived from mouse models, we then employed human breast cancer samples to determine the correlation of BRCA1 and GATA3." (PMID 34373738, 2021).
breast carcinoma (continued). "In total, seven TFs (HOXC11, FOXA1, SPDEF, SOX12, HOXC10, GATA3 and TFAP2A) were annotated to the breast cancer samples." (PMID 34712617, 2021). "On the other hand, considering the history of breast cancer, the immunoprofile of breast cancer such as ER, PR, HER2, GATA3, and GCDFP15, should be used to confirm the origin from breast cancer metastasis." (PMID 33776925, 2021). "By using our previously published resource of 43 invasive human breast cancers and the RNA prepared from microdissected FFPE sections of tumors 20, we assessed BRCA1 and GATA3 mRNA levels in 9 ER-positive and 10 ER-negative samples." (PMID 34373738, 2021). "This GATA3 mediation is one of the central components of the ESR1 complex that determines the binding potential and transcriptional targets in breast cancer cells." (PMID 33670895, 2021). "GATA3 is known to be a major factor involved in the regulation of ESR1 expression and is ubiquitously present in luminal A breast cancers." (PMID 34561764, 2021). "For examples, in human estrogen receptor positive (ER +) breast cancer MCF7 cells, the GATA3 gene has a broad epigenetic domain." (PMID 34238359, 2021). "The function of GATA3 in suppressing EMT and metastasis in breast cancers has been well studied in cell line models 19, 26-28." (PMID 34373738, 2021). "In a breast cancer cell line, TET2 was reported as a component of the estrogen receptor (ER)/GATA3 complex and was shown to be recruited in a GATA3-dependent manner." (PMID 34158086, 2021). "Taken together, the current work revealed that menin interacts both with GATA3 and FOXA1 in ER + breast cancer cells." (PMID 34561764, 2021). "In our study, GATA3 and GATA6 transcripts were identified as gene signatures for breast cancer and gastroesophageal cancer, respectively." (PMID 32850691, 2020). "IHC staining of mammaglobin, GATA3 and gross cystic disease fluid protein-15 (GCDFP-15) is used to help diagnose metastatic tumor from breast cancer." (PMID 32011488, 2020). "In conclusion, we confirmed that that lncRNA-LOC645166 promotes STAT3 activation by recruiting NF-κB to the promoter region of GATA3, thus eliciting ADR tolerance in Breast cancer cells." (PMID 32461377, 2020). "In addition, overexpressing GNAS-AS1 elevated M2 macrophage polarization and promoted the capabilities of proliferation, migration and invasion of ER+ breast cancer cells through directly repressing miR-433-3p, which could target GATA3 to markedly inhibit its expression." (PMID 32538432, 2020). "A phenotype switch from basal-like to luminal breast cancer can be achieved through the expression of FOXA1, GATA3 or ESR111–13." (PMID 32801338, 2020). "Importantly, we proposed a new modulator mechanism that GNAS-AS1 promoted proliferation, migration and invasion of ER+ breast cancer cells by inducing M2 macrophage polarization via regulating miR-433-3p/GATA3 axis, which may provide an effective strategy for breast cancer treatment." (PMID 32538432, 2020). "Associations were also observed for the cistromes of established breast cancer transcription factors (TFs); ESR1, FOXA1, and GATA3." (PMID 31910858, 2020). "To determine the Th2 lymphocyte phenotype in the canine mammary tumors, we assessed the expression of CCR2, GATA3, and IL-4." (PMID 32225066, 2020).
breast carcinoma (continued). "This is the first study that comprehensively characterized clinicopathological and prognostic features of breast cancers missing either of two canonical markers, CK7 and GATA3." (PMID 31718619, 2019). "GATA3 suppression promotes EMT, metastasis and suppresses cell differentiation and alters the tumor microenvironment by inducing angiogenesis in breast cancer." (PMID 31024232, 2019). "Our results further show that the GATA3-UTX-Dicer axis inhibits EMT, invasion, and metastasis of breast cancer cells in vitro and the dissemination of breast cancer in vivo." (PMID 31685800, 2019). "Several direct downstream targets of GATA3 in the luminal epithelium have been identified including FOXA1, a key regulator of ER binding in the breast cancer cells." (PMID 31408468, 2019). "Breast cancer metastases (n = 164) from various anatomical sites were retrospectively analyzed by immunohistochemistry for FOXA1, Nestin and GATA3 expression." (PMID 30819139, 2019). "If we want to apply the findings in this study to facilitate the diagnosis of metastatic breast cancer, we need to know the CK7 and GATA3 expression in matched pairs of primary and metastasis." (PMID 31718619, 2019). "The concurrent expression of GATA3, NR2F2, and FOXA1 in ERα positive breast carcinomas is intriguing." (PMID 31588232, 2019). "Inactivation of GATA3 results in failure of the mesenchymal-epithelial transition (MET), which increases breast cancer metastasis." (PMID 31588232, 2019). "It is well recognized that the GATA binding protein 3 (GATA3), a transcription factor, is a tumor suppressor in breast cancer." (PMID 31754326, 2019). "Our data provide a molecular basis for understanding the pathophysiological function of GATA3 and support the view that the GATA3-UTX-Dicer axis can serve as a potential therapeutic target in breast cancer." (PMID 31685800, 2019). "In another study, BRCA1 recruits GATA3 to the FOXC1 promoter to repress its expression in normal breast cells, inhibiting the development of the BLBC subtype of breast cancer." (PMID 30764547, 2019). "Altogether, we have presented evidence dissecting the role of the Notch3/GATA-3 axis in the EMT process, as well as in the inhibition of breast cancer metastasis." (PMID 30100605, 2018). "Such an effect would have provided an attractive explanation for the oncogenic activity of ZC3H8, as Gata-3 is essential for maintenance of mammary cell differentiation, and GATA-3 serves as a positive prognostic factor in human breast cancer." (PMID 30041613, 2018). "Analysis of different data sets of breast cancer patients showed that MYC overexpression anti-correlated with ESR1 and GATA3 transcript levels." (PMID 29523784, 2018). "Other markers of mammary differentiation such as GATA-3, mammaglobin, and BRST-2 (or gross cystic disease fluid protein 15) have been successfully employed in female breast cancer." (PMID 29116378, 2018). "Notch3 and GATA binding protein 3 (GATA-3) have been, individually, shown to maintain luminal phenotype and inhibit epithelial–mesenchymal transition (EMT) in breast cancers." (PMID 30100605, 2018). "As such, both GATA3 and FOXA1 are termed key luminal breast cancer‐defining genes and are expressed in virtually all ERα‐positive primary breast cancers." (PMID 29972720, 2018). "As expected and in line with literature, most ERα‐positive primary breast cancers we studied also expressed FOXA1 (n = 73/81, 90%; staining percentage range 3–100%, mean 70%) and GATA3 (n = 63/81, 78%; staining percentage 1–100%, mean 58%)." (PMID 29972720, 2018). "This work has characterized the DNA binding landscape of ERα in male breast cancer, along with its pioneer factors FOXA1, GATA3, and enhancer-enriched histone modification H3K4me1." (PMID 29396493, 2018).
breast carcinoma (continued). "Of the four biomarkers we detected, ESR1 is the only one in common with the reported signature for luminal breast cancers (ESR1, GATA3, FOXA1, XBP1, and cMYB)." (PMID 29868123, 2018). "In this study, we show that Ell3, ER(α), GATA3 and FOXA1 form a transcriptional complex to regulate IL-20 expression in ER(+) breast cancer cell lines." (PMID 28514748, 2017). "In conclusion, GATA3 and TRPS1 are distinctly high-expressed in breast cancer versus normal controls and predict better survival in patients with BC." (PMID 28423734, 2017). "Western blotting showed varied expression levels of GATA3 in keratinocytes (HaCaT), HNSCC cells (OEC-M1, SAS, FaDu and OC3), melanoma cells (A375) and breast cancer cells (MCF7 and T47D)." (PMID 28263977, 2017). "In contrast, luminal cancers express breast cancer differentiation markers (KRT20, CD24, ERBB2, and GATA3) and uroplakins which are markers of terminal urothelial differentiation." (PMID 28102366, 2017). "GATA3 and FOXA1 are considered ER-related genes because they are co-expressed with ER(α) in breast tumors and in breast cancer cell lines." (PMID 28514748, 2017). "ESR1 (estrogen receptor alpha), GATA3 (GATA Binding Protein 3), and CDH1 (E-cadherin) are amongst the genes most down-regulated by Twist expression and shown to be involved in the progression of breast cancer earlier." (PMID 28086829, 2017). "Expression of TBC1D9 and CEACAM6 was higher in GATA3 mutant MCF-7 cells, GATA3 mutant CAMA1 cells, and primary GATA3 mutant breast cancer cells, whereas expression of PPT1, CYBRD1, HOXC13, and AFF3 was higher in GATA3 wild type cells." (PMID 29262572, 2017). "In this study, we demonstrated that ER(α), GATA3 and FOXA1 form a transcriptional complex with Ell3 to regulate IL-20 expression in ER(+) breast cancer cells." (PMID 28514748, 2017). "In an inferred TRN, ESR1 interacts with other TFs such as AP1, GATA3, and CEBP to mediate distinct biological functions in breast cancer cells." (PMID 29051499, 2017). "Studies examining the effect of expressing wild type Gata3 in ER-negative cell lines such as MDA-MB-231 have shown that Gata3 favors expression of epithelial over mesenchymal markers and negatively regulates breast cancer metastasis." (PMID 29262572, 2017). "The LogicTRN analysis provides evidence that GATA3 and ESR1 are key regulators in E2-induced cell proliferation of breast cancer cells." (PMID 29051499, 2017). "In order to investigate the impact(s) of GATA3 on chromatin, we utilized the MET model in the MDA-MB-231 breast cancer cell line." (PMID 26922637, 2016). "ESR1, GATA3 and FOXA1 form part of the well-characterised estrogen receptor transcriptional network in ER+ breast cancer cells." (PMID 27997592, 2016). "We further validated binding of the TFs GATA3, FOXA1 and ESR1 to the enhancers activated in breast cancers using publicly available ChIP-seq data." (PMID 27833659, 2016). "It has been reported that GATA1 is overexpressed in aggressive breast cancer and GATA3, another GATA family member, inhibits breast cancer metastasis through increasing E-cadherin expression." (PMID 25726523, 2015). "GATA3, another GATA family member, inhibits breast cancer metastasis through increasing E-cadherin expression." (PMID 25726523, 2015). "We identified networks regulated by known cancer drivers such as GATA3 and FOXA1 (breast cancer), SOX17 and FOXA2 (endometrial cancer), and NFE2L2, SOX2, and TP63 (squamous cell lung cancer)." (PMID 25994056, 2015).
breast carcinoma (continued). "Both SNPs are located directly under the binding sites for a number of breast cancer-relevant transcription factors, including forkhead box M1 (FOXM1) and GATA binding protein 3 (GATA3)." (PMID 25652398, 2015). "Several proteins serve as pioneer factors contributing to ERα action in breast cancer, including FOXA1 and GATA3." (PMID 24962896, 2014). "To this end, we compared GATA3 transcript levels in the BLBC lines MDA-MB-468 (TNBC), MDA-MB-231 (Basal B) and Hcc1143 (TNBC) and in luminal breast cancer lines MCF7 and T47D to normal epithelial mammary cells." (PMID 25410484, 2014). "We find that gene expression patterns within early neoplasias are distinct from both normal and breast cancer patterns and identify a pattern of pro-oncogenic changes, including elevated transcription of ERBB2, FOXA1, and GATA3 at this early stage." (PMID 24887547, 2014). "We confirmed the presence of guanine insertion in GATA3 gene in our MCF7 stock and used a second luminal breast cancer cell line, T47D, wild-type for GATA3, as a control for our experiments." (PMID 24758297, 2014). "Accordingly, ectopic expression of GATA3 results in reversal of epithelial-mesenchymal transition (EMT), inhibition of dissemination and metastasis, and induction of differentiation in breast cancer cell lines and mouse models." (PMID 25410484, 2014). "The list of genes up-regulated in both neoplasia and breast cancer includes well-known Cancer Gene Census genes such as ERRB2, GATA3, and MUC1, among others." (PMID 24887547, 2014). "A functional link between GATA3 expression and the histone methyltransferase enhancer of zeste homolog 2 (EZH2) has been suggested, since EZH2 knockdown in basal-like breast cancer cells promotes the increase of GATA3 expression levels." (PMID 25479686, 2014). "Two studies have shown that two different GATA factors, GATA-3 and tricho-rhino-phalangeal syndrome type 1 (TRPS1), activate E-cadherin gene expression in breast cancer cells." (PMID 24040319, 2013). "STAT1-/- ERα+ mammary tumors also showed elevated transcription of genes characteristic of luminal breast cancers (for example, keratin 8, keratin 18, XBP1, GATA3, MYB, AREG, and FOXA1)." (PMID 22264274, 2012). "Several peer-reviewed publications have highlighted the joint regulation of the estrogen receptor-a (ESR1/ER-α), GATA3 and FOXA1 in breast cancer cells." (PMID 19104654, 2008). "The four different ESR1 probes on the array defined two primary ESR1-associated probe set clusters, including genes (for example, GATA3, KRT8, KRT18) commonly used to define luminal-type breast cancers." (PMID 17850661, 2007). "In SAGE (serial analysis of gene expression) studies we observed an intriguing significant correlation between GATA3 and MUC1 mRNA expression in breast carcinomas." (PMID 17078870, 2006). "It is interesting to note that GATA3 and MUC1 protein expression are positively correlated among normal breast samples as well as in breast carcinomas (τb = 0.44; p = 0.01)." (PMID 17078870, 2006). "To validate the relationship of GATA3 and MUC1 in breast cancer epithelial cell further, we performed an mRNA expression analysis of 36 primary breast carcinomas by means of real-time RT-PCR." (PMID 17078870, 2006). "Overall, these studies showed a consistently statistically significant correlation between GATA3 and MUC1 expression at the mRNA and protein levels by SAGE profiling (p = 0.002), real-time RT-PCR (p < 0.0001), and TMA (p = 0.01) in breast carcinomas." (PMID 17078870, 2006). "Recently we performed a cross-platform comparison between SAGE and DNA microarray profiles showing that the ESR1, GATA3, and MUC1 genes are very tightly co-expressed in breast carcinomas." (PMID 17078870, 2006).